SDCCAG8 (SHH signaling and ciliogenesis regulator SDCCAG8)
Description:
Plays a role in the establishment of cell polarity and epithelial lumen formation (By similarity). Also plays an essential role in ciliogenesis and subsequent Hedgehog signaling pathway that requires the presence of intact primary cilia for pathway activation. Mechanistically, interacts with and mediates RABEP2 centrosomal localization which is critical for ciliogenesis.
Synonyms: hCCCAP; CCCAP; NPHP10; HSPC085; NY-CO-8; SLSN7; BBS16; CCCAP SLSN7
Tractability: PROTAC: ubiquitination databases record sites on it; its protein half-life has been measured.
Gene: Protein-coding gene on chromosome 1 (243,255,349 to 243,500,095, forward strand). Ensembl gene ENSG00000054282.
Subcellular location: Cytoplasm, cytoskeleton, microtubule organizing center, centrosome, centriole; Cytoplasm, cytoskeleton, microtubule organizing center, centrosome; Cytoplasm, cytoskeleton, cilium basal body; Cell junction; Cytoplasm (Isoform 2)
Subcellular location (Human Protein Atlas): Basal body; Centrosome; Primary cilium
Pathways (Reactome):
Cell Cycle: AURKA Activation by TPX2; Loss of Nlp from mitotic centrosomes; Loss of proteins required for interphase microtubule organization from the centrosome; Recruitment of NuMA to mitotic centrosomes; Recruitment of mitotic centrosome proteins and complexes; Regulation of PLK1 Activity at G2/M Transition
Organelle biogenesis and maintenance: Anchoring of the basal body to the plasma membrane
Gene Ontology:
Molecular function: protein binding
Biological process: regulation of cilium assembly; establishment of cell polarity; microtubule organizing center organization; neuron migration; tube formation; centrosome cycle
Cellular component: cell-cell junction; centriole; centrosome; ciliary basal body; cytosol; anchoring junction; centriolar satellite; cytoplasm; photoreceptor cell cilium
Genetic constraint (gnomAD): Loss-of-function variants: 57 observed, 84.33 expected, observed/expected ratio (o/e) 0.68, 90% interval 0.55 to 0.84. The upper end of that interval is the gene's LOEUF score, 0.84, which puts it in group 3 of 6, group 1 being the genes least tolerant of losing a copy. Missense variants: 656 observed, 724.6 expected, observed/expected ratio (o/e) 0.91, 90% interval 0.85 to 0.97. Synonymous variants: 229 observed, 264 expected, observed/expected ratio (o/e) 0.87, 90% interval 0.78 to 0.97.
Gene-disease validity (ClinGen):
ClinGen rates the evidence that SDCCAG8 causes each of these diseases.
Bardet-Biedl syndrome 16 (autosomal recessive): Definitive. Any Bardet-Biedl syndrome in which the cause of the disease is a mutation in the SDCCAG8 gene.
Homologues: Orthologues: chimpanzee SDCCAG8 (99% identical), macaque SDCCAG8 (95% identical), pig SDCCAG8 (82% identical), dog SDCCAG8 (81% identical), guinea pig SDCCAG8 (78% identical), mouse Sdccag8 (78% identical), rat Sdccag8 (76% identical), rabbit SDCCAG8 (73% identical).